KEAP1 (kelch like ECH associated protein 1)
Diseases named in the same sentence as KEAP1 in open-access papers (continued):
Sharing a sentence is not in itself a finding about the gene and the disease.
thyroid (5 papers, 2014 to 2025). "Our findings indicate that KEAP1 mutations are functionally relevant and may represent a potential driver of thyroid tumorigenesis, as observed in other malignancies." (PMID 41573641, 2025). "In both pediatric and adult thyroid tumors, we identified KEAP1 mutations with concurrent MAPK driver mutations, indicating potential cooperation between NRF2 and MAPK pathways in thyroid tumorigenesis." (PMID 41573641, 2025). "In recent years, several studies identified genes that cooperate with RAS mutations in the pathogenesis or progression of thyroid and other types of cancers, such as NF1, APC, PTEN, KEAP1, NF2 and others." (PMID 34065786, 2021). "Additionally, an analysis of PTC samples from The Cancer Genome Atlas (TCGA) revealed epigenetic silencing of KEAP1 through promoter hypermethylation, further linking KEAP1/NRF2 pathway dysregulation to thyroid carcinogenesis." (PMID 41573641, 2025). "The present focused review of the thyroid field suggests that the Keap1/Nrf2 system might also have utility in the search for biomarkers and/or drug targets for thyroid pathologies." (PMID 33158045, 2020). "In patients with KEAP1 germline mutations, excessive NRF2 activity in the thyroid gland may exert a cytoprotective effect even against cells subjected to apoptosis by severe ROS generation, resulting in thyroid hyperplasia with scarce degradation." (PMID 39373520, 2025).
type 1 diabetes (5 papers, 2018 to 2024). "It has been reported that HDAC3 inhibition regulates Keap1/Nrf2 in tumor cell lines or type 1 diabetes-associated aortic pathologies, which is through modulating the expression of miR-200a that binds to the 3′-terminal region of the Keap1 mRNA to inhibit its translation." (PMID 31101061, 2019). "The Keap1/Nrf2/HO‐1 signaling pathway, a classic pathway related to oxidative stress, has been reported to be involved in many diseases, including osteoclastogenesis, type 1 diabetes, and nephrotoxicity." (PMID 37773689, 2023). "Similarly, resveratrol attenuates testicular apoptosis in type 1 diabetic mice through the upregulation of Nrf2 expression and function by Akt-mediated Nrf2 activation and p62-dependent Keap1 degradation." (PMID 30622677, 2018).
acute myeloid leukemia (4 papers, 2021 to 2023). Acute myeloid leukemia (AML) is a group of neoplasms arising from precursor cells committed to the myeloid cell-line differentiation. "In this case-control study, the expression of genes encoding Nrf2, Keap1, Bcl2, Bcl- XL and Bax in 40 acute myeloid leukemia (AML) patients were compared with 40 normal individuals in the Iranian population." (PMID 34400968, 2021). "Patients with acute myeloid leukemia (AML) with higher KEAP1 expression had worse overall survival (OS)." (PMID 37251921, 2023).
allergic rhinitis (4 papers, 2021 to 2025). Inflammation of the nasal mucous membranes caused by an IgE-mediated response to external allergens. "In allergic rhinitis, Nrf2/Keap1 (Kelch-like ECH-associated protein 1) and NF-B pathways are among the known signaling pathways in oxidative stress." (PMID 41154690, 2025). "As commonly known signaling pathways in oxidative stress, Nrf2/Keap1 (Kelch-like ECH-associated protein 1) and NF-κB pathways have been covered in allergic rhinitis." (PMID 34439514, 2021).
brain injury (4 papers, 2019 to 2024). Acute and chronic (see also brain INJURIES, CHRONIC) injuries to the brain, including the cerebral hemispheres, CEREBELLUM, and brain STEM. "Several scientific studies have demonstrated the therapeutic potential of targeting the NRF2/Kelch‐like ECH‐associated protein 1 (KEAP1) pathway in HI‐induced brain injury." (PMID 39496476, 2024). "Our results indicate that CD28 deficiency has a protective effect on thoracic blast exposure-induced brain injury that might be associated with the PI3K/Nrf2/Keap1 signaling pathway." (PMID 31885821, 2019). "Our data indicate that ROS generation, apoptosis, and activation of the PI3K/Nrf2/Keap1 signaling pathway play essential roles in the thoracic blast exposure-induced brain injury." (PMID 31885821, 2019).
cholangiocarcinoma (4 papers, 2021 to 2025). A carcinoma that arises from the intrahepatic biliary tree (intrahepatic cholangiocarcinoma) or from the junction, or adjacent to the junction, of the right and left hepatic ducts (hilar cholangiocarcinoma). "In this study, FOXO3 was found to promote the transcription of KEAP1, and this FOXO3–KEAP1 axis was downregulated with a corresponding hyperactivation of NFR2 in clinical cholangiocarcinoma samples." (PMID 35883815, 2022). "Moreover, it has been reported that FOXO3A can regulate chemotherapy and targeted drug resistance; for example, in cholangiocarcinoma, FOXO3A inactivation through the Keap1–Nrf2 axis leads to chemotherapy resistance." (PMID 40940943, 2025).
endometritis (4 papers, 2024 to 2025). An acute or chronic, usually bacterial infectious process affecting the endometrium. "This review explores the potential therapeutic benefits of targeting the Nrf2/Kelch-like ECH-associated protein 1 (Keap1)/NF-κB signaling pathway to alleviate LPS-induced endometritis." (PMID 39408650, 2024). "Here, we observed that SeY acts as a preventive protective agent to attenuate goat endometritis through MAPK, NF-κB, and NRF2/kelch like ech associated protein 1 (KEAP1) signaling pathways under high cortisol background." (PMID 40075974, 2025). "In conclusion, this review provides a comprehensive understanding of the critical roles played by the Nrf2/Keap1/NF-κB signaling pathways in mediating inflammatory and oxidative responses in LPS-induced endometritis in vitro." (PMID 39408650, 2024). "However, under oxidative stress, such as that induced by LPS in endometritis, Nrf2 dissociates from Keap1, moves into the nucleus, and triggers the transcription of genes under the antioxidant response element (ARE) promoter." (PMID 39408650, 2024). "The prevention of endometritis in BEECs was attributed to the Keap1/Nrf2 signaling pathway." (PMID 39408650, 2024). "Overall, our results suggested that the NRF2/ KEAP1, MAPK, and NF-κB signaling pathways are important pathways for SeY protection against E. coli-induced endometritis under high cortisol background." (PMID 40075974, 2025). "The buffaloes with endometritis had considerably higher expression levels of TLR4, IL-8, IL-17, NFKB, SLCA11A1, NCF4, Keap1, HMOX1, OXSR1, ST1P1, and SERP1." (PMID 39195794, 2024). "Our findings showed that the buffaloes with endometritis had significantly higher TLR4, IL-8, IL-17, NFKB, SLCA11A1, NCF4, Keap1, HMOX1, OXSR1, ST1P1, and SERP1 expression levels." (PMID 39195794, 2024). "TLR4, IL-8, IL-17, NFKB, SLCA11A1, NCF4, Keap1, HMOX1, OXSR1, ST1P1, and SERP1 were manifestly expressed at much higher levels in the buffaloes with endometritis." (PMID 39195794, 2024). "The following genes were assessed for their expression levels using real-time PCR in both the normal and endometritis-affected buffaloes: immune (TLR4, IL-8, IL-17, NFKB, SLCA11A1, and NCF4) and antioxidant (SOD, CAT, NDUFS6, Nrf2, Keap1, PRDX2, HMOX1, OXSR1, ST1P1, and SERP1)." (PMID 39195794, 2024).
epilepsy (4 papers, 2020 to 2025). A brain disorder characterized by episodes of abnormally increased neuronal discharge resulting in transient episodes of sensory or motor neurological dysfunction, or psychic dysfunction. "This study aims to analyze the relationship between the Kelch-like ECH-associated protein 1 (Keap1)/Nuclear factor-erythroid 2-related factor 2 (Nrf2) and Epilepsy (EP), as well as its mechanism of action." (PMID 38733688, 2024).
inflammatory bowel disease (4 papers, 2024 to 2026). A spectrum of small and large bowel inflammatory diseases of unknown etiology. "The Nrf2/Keap1 signaling pathway plays a multifaceted and dynamic role in the pathophysiology of inflammatory bowel disease." (PMID 41462607, 2025).
ischemia reperfusion injury (4 papers, 2017 to 2023). Adverse functional, metabolic, or structural changes in ischemic tissues resulting from the restoration of blood flow to the tissue (reperfusion), including swelling; hemorrhage; necrosis; and damage from free radicals. "The study aims to investigate the effect of JAK2 signaling on the expression of the Keap1/Nrf2 axis, spermatogenesis, and the Sertoli cells (Sc) junctions in an animal model of testicular ischemia reperfusion injury (tIRI)." (PMID 37759514, 2023).
lung carcinoid (4 papers, 2019 to 2022). "A KEAP1 hypermethylation and Loss of Heterozygosity at KEAP1 gene locus was also observed in nearly half of lung carcinoids." (PMID 31126053, 2019). "The epigenetic silencing by KEAP1 hypermethylation in lung carcinoids was then investigated in carcinoid tissues from 47 patients." (PMID 31126053, 2019). "This is the first study that has described the effects of KEAP1 silencing on the regulation of NRF2 activity in lung carcinoids cells." (PMID 31126053, 2019). "The KEAP1 silencing studies by siRNAs performed both in H720 and in H727 cell lines strongly indicate that KEAP1 is also a master regulator of NRF2 in lung carcinoids cells." (PMID 31126053, 2019). "The epigenetic deregulation of the KEAP1/NRF2 by a KEAP1 promoter hypermethylation system appears to be a frequent event in lung carcinoids." (PMID 31126053, 2019). "We decided to investigate the effect of KEAP1 silencing in lung carcinoids by performing functional investigation in H720 and H727 cell lines." (PMID 31126053, 2019). "The epigenetic status of KEAP1 was correlated to clinical-pathological features of both typical and atypical lung carcinoids." (PMID 31126053, 2019). "Hypermethylation at the promoter region of the KEAP1 was detected in one third of cell lines and its effect on the modulation KEAP1 mRNA levels was also confirmed by in vitro 5-Azacytidine treatment on lung carcinoid, small lung cancer and adenocarcinoma cell lines." (PMID 31159323, 2019). "Additionally, we perform the first epigenetic profile of KEAP1 promoter region in lung carcinoid tissues together with the genetic screening of the KEAP1 and NFE2L2 genes and LOH analysis." (PMID 31126053, 2019). "The link between the NRF2 system of sensing environmental stress and mTOR may suggest a possible role of KEAP1/NRF2 deregulation observed in lung carcinoids in prediction to response to mTOR pharmacological inhibition in these tumors." (PMID 31126053, 2019). "Despite all these considerations, the KEAP1 silencing studies support the hypothesis that KEAP1 acts in lung carcinoids by modulating the levels of NRF2 and the NRF2-detoxification enzymes TXNRD1 and NQO1." (PMID 31126053, 2019). "Here we describe the results obtained from the first comprehensive genetic and epigenetic profile of KEAP1 and NFE2L2 genes in a collection of lung carcinoid tumors." (PMID 31126053, 2019). "In conclusion, our findings of KEAP1 methylation and related NRF2 pathway deregulation in lung carcinoids add important data to the poorly uncovered epi-profile of lung NET." (PMID 31126053, 2019). "The effects of KEAP1 silencing on NRF2 activity was investigated in H720 and H727 carcinoid cell lines and results were compared with those obtained by molecular profiling of KEAP1 and NFE2L2 in a collection of 47 lung carcinoids." (PMID 31126053, 2019). "The KEAP1 promoter methylation level was evaluated on DNA obtained from a total of all lung carcinoid tissues and 12 normal lung tissues from non-neoplastic patients (NL)." (PMID 31126053, 2019).
lung disease (4 papers, 2022 to 2025). "In this study, we analyzed the participation of the polymorphisms of NFE2L2 and KEAP1 genes in the mechanisms of damage in lung disease patients with SARS-CoV-2 infection." (PMID 36613859, 2022). "Since most respiratory diseases involve inflammation and oxidative reactions, developing more natural products as Nrf2/Keap1 pathway inducers for lung disease treatment is promising." (PMID 38519984, 2024). "Studies have found that Peimisine can inhibit oxidative stress, DNA damage, apoptosis and autophagy dysregulation through the NRF2/KEAP1 and JNK/MAPK-dependent pathways, thereby slowing down the pathological progression of lung diseases." (PMID 40718794, 2025).
lymph node metastasis (4 papers, 2012 to 2022). "Moreover, Keap1 expression was negatively correlated with lymph node metastasis, higher levels of Keap1 expression were more likely associate without lymph node metastasis (P = 0.017)." (PMID 34466284, 2021). "Early stage (I) tumors without lymph node metastasis had higher levels of Keap1 expression compared with late-stage tumors (II, III) with the presence of lymphatic metastasis." (PMID 34466284, 2021). "Keap1 expression was inversely correlated with the clinical stage and lymph node metastasis and early-stage tumors (I) without lymph node metastasis had higher levels of Keap1 expression compared with late-stage tumors (II and III)." (PMID 34466284, 2021).
pancreatic adenocarcinoma (4 papers, 2011 to 2024). "In agreement with this, ROS overproduction renders pancreatic adenocarcinoma cells susceptible to cell death, and the progression of pancreatic adenocarcinoma often coincides with mutations inactivating Keap-1 and rendering NRF2 constitutively active." (PMID 38782891, 2024). "We assessed immunohistochemically the expression of 8-OHdG and Keap1 in precisely characterized material of 69 pancreatic adenocarcinoma patients." (PMID 25879528, 2015). "Partly as a continuation to that study, our specific aim was here to evaluate the role of both Keap1 and 8-OHdG in an independent material of pancreatic adenocarcinomas." (PMID 25879528, 2015). "The present results show that expression of Nrf2’s main regulator, Keap1, is highly significant prognostic factor in pancreatic adenocarcinomas in terms of RFS and PCSS." (PMID 25879528, 2015).
stomach adenocarcinoma (4 papers, 2017 to 2024). "Furthermore, the analysis of pan-cancer TCGA data revealed a mild but significant correlation where some ARID1A-mutated tumor subtypes present elevated KEAP1 mRNA levels (e.g., stomach adenocarcinoma—STAD, and colon adenocarcinoma—COADREAD)." (PMID 39272807, 2024). "Furthermore, stratification of patients by ARID1A mutational status confirmed this relationship, where some ARID1A-mutated cancer subtypes (e.g., stomach adenocarcinoma—STAD) appear to upregulate KEAP1 compared to wild-type." (PMID 39272807, 2024). "Molecular profiling of stomach adenocarcinoma patient tissues has identified mutations in KEAP1, NFE2L2 and CUL3, with KEAP1 mutations being the most prevalent." (PMID 33276631, 2020). "Somatic mutations of the KEAP1 gene, especially in the BTB domain encoded by exon 2 have been identified in several solid cancers, e.g., NSCLC and gastric adenocarcinoma." (PMID 28767070, 2017).
tauopathies (4 papers, 2020 to 2026). "Previously, our group described that DMF has beneficial effects in the AAV-TAUP301L tauopathy model through two mechanisms: DMF induces NRF2 pathway involving KEAP1, as well as PI3K/AKT/GSK-3-dependent pathways." (PMID 41486173, 2026). "DMF was previously shown to exert a double mechanism of Nrf2 activation by disrupting the KEAP1/Nrf2 interaction and through the glycogen synthase kinase 3 beta (GSK3β)/Nrf2 signaling pathway, in a tauopathy mouse model." (PMID 33096789, 2020). "Moreover, our custom‐designed peptide may have the potential to rescue the KEAP1/NRF2/ARE pathway and thus arrest tauopathies." (PMID 35917404, 2022). "Thus, DMF activation of NRF2 through two distinct proteolytic pathways, a KEAP1 dependent one and the other mediated by GSK-3β phosphorylation, makes this compound a promising therapy for neurodegenerative diseases as tauopathies, where either KEAP1 or GSK-3β activities are altered." (PMID 32756501, 2020).
Ureteral obstruction (4 papers, 2016 to 2023). Obstruction of the flow of urine through the ureter. "Until our report, only studies showing positive effects of Keap1 knockdown in renal damage models, such as protection from tubular damage in reperfusion or ureteral obstruction, had been published." (PMID 36979025, 2023). "Keap1 hypomorphic mice showed a significant increase in the expression of Nrf2, and a renoprotective effect was found in a unilateral ureteral obstruction model." (PMID 30796317, 2019). "Primary dilatation of the renal collecting system without ureteral obstruction was induced by Keap1 knockout and the expression of aquaporins with spontaneous mutations, which caused urinary hyperproduction and secondary dilatation of the renal collecting system." (PMID 37893447, 2023).
vitiligo (4 papers, 2020 to 2025). Generalized well circumscribed patches of leukoderma that are generally distributed over symmetric body locations and is due to autoimmune destruction of melanocytes. "The study’s findings of reduced CUL3 and NRF2 expression in vitiligo tissues align with the concept that the Keap1/CUL3/NRF2 axis is disrupted, impairing the cellular antioxidant response and predisposing melanocytes to oxidative damage." (PMID 40723924, 2025). "In summary, the NRF2/KEAP1 system is important in vitiligo but far more specific than a therapeutic target." (PMID 36671405, 2022). "This Keap1/NRF2/ARE axis is thus essential for maintaining cellular redox homeostasis and has been implicated as a promising therapeutic target in vitiligo, where enhanced NRF2 activity may counteract oxidative damage and melanocyte loss." (PMID 40723924, 2025). "The Keap1/NRF2/ARE pathway is critical for melanocyte protection against oxidative damage; however, the role of Cullin-3 (CUL3), a scaffold for E3 ubiquitin ligases that regulate NRF2 degradation, and its interplay with inflammatory mediators in vitiligo pathogenesis are underexplored." (PMID 40723924, 2025).
adenoma (3 papers, 2021 to 2022). A neoplasm arising from the epithelium. "Loss of Atg5 (autophagy related 5) or Atg7 in the mouse liver is associated with damaged mitochondria and peroxisomes, lipid droplets and accumulation of protein aggregates with p62 and Keap1, leading to sustained Nrf2 activation that causes benign adenoma." (PMID 34206503, 2021). "Upon decreased rates of autophagy, phosphorylated p62 accumulates with Keap1 in structures of the human liver, indicating Nrf2 activation that contributes to adenoma formation and the development of HCC." (PMID 34206503, 2021). "Accumulated SQSTM1/p62 then traps Keap1, a negative regulator of NRF2, and releases NRF2 from Keap1-mediated regulation, leading to the NRF2 signaling activation and enhancing adenoma formation in the liver." (PMID 36139512, 2022). "Notably, the mRNA levels for Nqo1 in tumor and peri-tumoral tissues in WT (i.e. Gstp−/−: ApcMin/+: Nrf2+/+: Keap1+/+) mice were highly variable among 12 randomly selected individual animals, suggesting no consistent changes in Nrf2-transcriptional activity during adenoma development." (PMID 34526660, 2021). "Our results show that neither genetic (by Keap1 knockdown) nor pharmacological (by a potent activator, the cyanoenone TBE-31) Nrf2 activation affects adenoma development at the early stages." (PMID 34526660, 2021).